MYH9 (myosin heavy chain 9)
Description:
Cellular myosin that appears to play a role in cytokinesis, cell shape, and specialized functions such as secretion and capping. Required for cortical actin clearance prior to oocyte exocytosis (By similarity). Promotes cell motility in conjunction with S100A4. During cell spreading, plays an important role in cytoskeleton reorganization, focal contact formation (in the margins but not the central part of spreading cells), and lamellipodial retraction; this function is mechanically antagonized by MYH10. (Microbial infection) Acts as a receptor for herpes simplex virus 1/HHV-1 envelope glycoprotein B.
Synonyms: NMMHC-IIA; NMMHCA; NMHC-II-A; MHA; FTNS; EPSTS; BDPLT6; DFNA17; MATINS
Tractability: Antibody: UniProt places it where antibodies can reach, with high confidence; its Gene Ontology location is reachable by antibodies, with high confidence. PROTAC: UniProt records ubiquitination sites on it; ubiquitination databases record sites on it; its protein half-life has been measured; a small molecule that binds it is known.
Gene: Protein-coding gene on chromosome 22 (36,281,279 to 36,388,010, reverse strand). Ensembl gene ENSG00000100345.
Subcellular location: Cytoplasm, cytoskeleton; Cytoplasm, cell cortex; Cytoplasmic vesicle, secretory vesicle, Cortical granule; Cell membrane
Subcellular location (Human Protein Atlas): Actin filaments; Plasma membrane; Cytosol; Nuclear bodies
Pathways (Reactome):
Signal Transduction: RHO GTPases Activate ROCKs; RHO GTPases activate CIT; RHO GTPases activate PAKs; RHO GTPases activate PKNs
Disease: CD163 mediating an anti-inflammatory response; FCGR3A-mediated phagocytosis; Signaling by ALK fusions and activated point mutants
Developmental Biology: EPHA-mediated growth cone collapse; Sema4D induced cell migration and growth-cone collapse
Sensory Perception: Sensory processing of sound by inner hair cells of the cochlea; Sensory processing of sound by outer hair cells of the cochlea
Immune System: Regulation of actin dynamics for phagocytic cup formation
Vesicle-mediated transport: Translocation of SLC2A4 (GLUT4) to the plasma membrane
Gene Ontology:
Molecular function: actin binding; actin filament binding; ADP binding; ATP binding; cadherin binding; identical protein binding; integrin binding; microfilament motor activity; protein binding; protein domain specific binding; protein homodimerization activity; protein-membrane adaptor activity; RNA binding; virus receptor activity; cytoskeletal motor activity
Biological process: actin cytoskeleton organization; actin filament-based movement; actomyosin structure organization; angiogenesis; blood vessel endothelial cell migration; cytokinetic process; lysosome localization; membrane protein ectodomain proteolysis; monocyte differentiation; negative regulation of actin filament severing; plasma membrane repair; platelet formation; protein transport; regulated exocytosis; regulation of plasma membrane repair; symbiont entry into host cell; cortical granule exocytosis; integrin-mediated signaling pathway; leukocyte migration; phagocytosis, engulfment; positive regulation of protein processing in phagocytic vesicle; vesicle fusion to plasma membrane; actin filament-based process; cell differentiation; cell morphogenesis; and 2 more
Cellular component: actin cytoskeleton; actomyosin; actomyosin contractile ring; cell leading edge; cell surface; cleavage furrow; COP9 signalosome; cytoplasm; cytoplasmic side of plasma membrane; cytosol; extracellular exosome; immunological synapse; membrane; myosin II complex; myosin II filament; nucleus; plasma membrane; protein-containing complex; ruffle; stress fiber; uropod; cortical granule; exocytic vesicle; focal adhesion; myosin filament; and 10 more
Genetic constraint (gnomAD): Loss-of-function variants: 29 observed, 248.88 expected, observed/expected ratio (o/e) 0.12, 90% interval 0.086 to 0.16. The upper end of that interval is the gene's LOEUF score, 0.16, which puts it in group 1 of 6, group 1 being the genes least tolerant of losing a copy. Missense variants: 1,803 observed, 2,672.1 expected, observed/expected ratio (o/e) 0.67, 90% interval 0.65 to 0.7. Synonymous variants: 1,047 observed, 1,097.9 expected, observed/expected ratio (o/e) 0.95, 90% interval 0.91 to 1.
Gene-disease validity (ClinGen):
ClinGen rates the evidence that MYH9 causes each of these diseases.
macrothrombocytopenia and granulocyte inclusions with or without nephritis or sensorineural hearing loss (autosomal dominant): Definitive.
Homologues: Orthologues: chimpanzee MYH9 (100% identical), macaque MYH9 (99% identical), dog MYH9 (98% identical), guinea pig MYH9 (98% identical), mouse Myh9 (97% identical), rat Myh9 (97% identical), rabbit MYH9 (96% identical), pig MYH9 (95% identical), tropical clawed frog myh9 (86% identical), zebrafish myh9a (77% identical), zebrafish myh9b (72% identical). Paralogues in human: MYH10 (78% identical), MYH11 (76% identical), MYH14 (65% identical), MYH7 (42% identical), MYH6 (41% identical), MYH3 (41% identical), MYH8 (41% identical), MYH1 (41% identical), MYH2 (41% identical), MYH7B (41% identical), MYH4 (41% identical), MYH13 (40% identical), and 32 more.
Diseases named in the same sentence as MYH9 in open-access papers:
MYH9 is named in the same sentence as 249 diseases in open-access papers, as found by Europe PMC text mining. Sharing a sentence is not in itself a finding about the gene and the disease. The quoted sentences say what the papers report.
Thrombocytopenia (68 papers, 2008 to 2026). A reduction in the number of circulating thrombocytes. "MYH9-RD is characterized by sensorineural hearing loss, macrothrombocytopenia, thrombocytopenia, hematuria/proteinuria, glomerulonephritis, cataracts purpura, and mucosal bleeding." (PMID 41751538, 2026). "To reduce the risk of MYH9-RD misdiagnosis, we recommend assessing mean platelet diameter and granulocyte inclusions in patients with unexplained proteinuria and refractory thrombocytopenia." (PMID 40416435, 2025). "Our findings demonstrate that a significant proportion of children who present with thrombocytopenia harbor genetic variants associated with congenital disease, with MYH9 being the most frequently affected gene." (PMID 41300679, 2025). "MYH9 mutations are associated with several human syndromes, now grouped as MYH9-related disorders that include hearing loss, kidney disease, thrombocytopenia, and cataracts." (PMID 40464565, 2025). "Mutations associated with thrombocytopenia in autosomal dominant diseases first highlighted the significance of the MYH9 gene." (PMID 39149512, 2024). "Here, we report a child with pathogenic missense variants in SCN1A and MYH9 simultaneously, presenting with phenotypes of recurrent seizures and thrombocytopenia." (PMID 39202364, 2024). "Human MYH9 gene mutations are associated with a group of autosomal dominant disorders, collectively known as MYH9-related disorders, which are characterised by thrombocytopenia." (PMID 38162645, 2023). "Meanwhile, in humans, MYH9 also plays an important role, as MYH9 mutation leads to thrombocytopenia." (PMID 37762538, 2023). "The novel concept implies that the R1933X mutation in the MYH9 gene is associated not only with thrombocytopenia, but also with qualitative structural and functional defects in platelets." (PMID 36404341, 2022). "Mutations of MYH9 in humans lead to a syndromic, autosomal dominant disorder that is called MYH9-related disease (MYH9-RD) and characterized by congenital thrombocytopenia with giant platelets and the inclusion of NMHC IIA in the cytoplasm of neutrophils." (PMID 35740994, 2022). "It has been shown that in patients with a heterozygous mutation C5797T (R1933X) in the MYH9 gene, hemorrhagic manifestations of varying severity are due not only to thrombocytopenia but also to qualitative structural and functional defects in platelets." (PMID 36404341, 2022). "These multiple qualitative platelet abnormalities, in combination with thrombocytopenia, contribute to bleeding risk in the MYH9-related disorder." (PMID 36404341, 2022). "TPO-receptor agonists were first explored in Inherited Thrombocytopenias in 2010 in a phase 2 trial of Eltrombopag in 12 patients with Myosin Heavy Chain 9 (MYH9) mutations." (PMID 34059198, 2021). "Since childhood our patient had shown macro-thrombocytopenia, deafness and bleeding tendency (epistaxis and menorrhagia), but she was misdiagnosed until 30 years when our Centre identified an MYH9 de novo allelic variant." (PMID 33308197, 2020). "Here, we report 50 MYH9‐RD patients with 28 rare variants in MYH9 found in a group of 3,031 patients (of whom 764 were classified as having thrombocytopenia) and over 13,000 controls." (PMID 31562665, 2020). "We first investigated the correlation between the position of variants in the MYH9 protein and the degree of thrombocytopenia, by dividing patients into two groups according to the platelet count being below (severe/moderate) or above 50 × 109/L (mild)." (PMID 31562665, 2020). "Presence of giant platelets and thrombocytopenia suggested molecular investigation for suspected MYH9 mutations." (PMID 33308197, 2020). "Rarely, thrombocytopaenia and glomerular disease can result from mutations in the myosin heavy chain 9 (MYH9) gene." (PMID 26519297, 2015).
Thrombocytopenia (continued). "Previous work found that the inhibitory action of type I collagen on PPF is dependent on myosin IIA, the only isoform expressed in Mks and platelets and is encoded by the MYH9 gene, whose mutations cause thrombocytopenia." (PMID 20027303, 2009). "In this patient, the MYH9 variant likely explains thrombocytopenia; the APC mutation, possibly incidental, may have broader immunological effects, as suggested by studies on APC mutations affecting T-cell function." (PMID 40941697, 2025). "MYH9 has been known to cause an autosomal-dominant disease called MYH9-related disorder (MYH9-RD), characterized by large platelets and thrombocytopenia as well as increased risk of progressive nephropathy, sensorineural deafness, pre-senile cataract, and aberration of liver enzymes." (PMID 36175409, 2022). "The thrombocytopenia in the child and her mother is explained by the MYH9 variant." (PMID 34573976, 2021). "DIAPH1-related thrombocytopenia is an autosomal dominant defect with macrothrombocytopenia and variable neutropenia, as well as hearing loss beginning in the first decade of life (at much younger ages than in MYH9-RD)." (PMID 33926054, 2021). "Mutations in MYH9 have been associated with hearing disorders, kidney defects and thrombocytopenia." (PMID 24130771, 2013). "BACKGROUND: May-Hegglin anomaly, a rare autosomal dominant disorder caused by MYH9 mutations, is characterized by the classic "triad" of thrombocytopenia, giant platelets, and granulocyte cytoplasmic inclusion bodies; some patients also present non-hematological symptoms." (PMID 41904450, 2026). "MYH9 plays a role in platelet contraction, modulation of platelet shape, and is associated with thrombocytopenia, among other crucial platelet functions which could have significant implications for platelet function, as well as the development and progression of thrombotic diseases." (PMID 39149512, 2024). "In conclusion, from our digenic network, we proposed that in the cerebral cortex, the variant of MYH9 might work as a modifier of SCN1A and, in this family, led to intra-family seizure phenotype variability, whereas in the bone marrow, the variant of MYH9 has probably led to thrombocytopenia." (PMID 39202364, 2024). "Treatment options for patients with MYH9-related thrombocytopenia can be grouped into two categories: curative and hemorrhage prevention and management." (PMID 41300679, 2025). "Our cohort confirms that MYH9-related disease is the most common genetically confirmed inherited thrombocytopenia in children." (PMID 41300679, 2025). "The only currently available curative treatment for patients with MYH9-related thrombocytopenia remains hematopoietic stem cell transplant." (PMID 41300679, 2025). "Eleven subjects (31.4%) were found to have bleeding disorders, including four with VWD, two each with hemophilia A and thrombocytopenia, and one each with factor VII deficiency, platelet dysfunction, and MYH9-related disorder." (PMID 39812819, 2025). "Congenital thrombocytopenia can be classified by platelet size: MYH9-related disease, Bernard–Soulier syndrome, and GPIIb/IIIa-induced thrombocytopenia, which are relatively frequent, are classified as congenital “macro” thrombocytopenia." (PMID 37957517, 2024). "MYH9-RD is an autosomal dominant genetic disease characterized by thrombocytopenia and large platelets." (PMID 39404399, 2024). "MYH9-RD (autosomal dominant) is characterized by the presence of congenital thrombocytopenia with giant thrombocytes and leucocyte inclusions." (PMID 39273383, 2024). "The thrombocytopenia of the patient can only be explained by the variant of MYH9, which means the variant in SCN1A accounts for the seizure phenotype, and the variant in MYH9 leads to thrombocytopenia in the bone marrow of the patient independently." (PMID 39202364, 2024).
Thrombocytopenia (continued). "MYH9-related disorder (MYH9-RD) is one such pathology characterized by thrombocytopenia and giant platelets with the presence of cytoplasmic inclusion bodies in the granulocytes." (PMID 38558752, 2024). "ITP, a common condition characterized by isolated thrombocytopenia, can often lead to the misdiagnosis of relatively rare MYH9-RDs." (PMID 38134071, 2023). "The detailed family history sheds more light on the hereditary nature of thrombocytopenia in this family and further supports the diagnosis of MYH9-RDs." (PMID 38134071, 2023). "MYH9-related disorders (MYH9-RDs) encompass a spectrum of rare genetic conditions characterized by diverse clinical presentations and isolated thrombocytopenia." (PMID 38134071, 2023). "Since platelet macrocytosis, along with thrombocytopenia, is one of the characteristic features of the MYH9-related disorders, we used scanning electron microscopy to compare platelet size in the patients examined versus a healthy donor." (PMID 36404341, 2022). "Although in the remaining four patients the genetic diagnosis is not available, their family history and clinical/laboratory features allowed us to include them in the MYH9-related thrombocytopenia patients." (PMID 36507135, 2022). "Taken together, these data strongly suggest that thrombocytopathy causes hemostatic abnormalities, aggravating the bleeding phenotype due to thrombocytopenia in MYH9-related disorders." (PMID 36404341, 2022). "First, only patients affected by ANKRD26-RT and MYH9-RD were investigated; however, they are among the most frequent forms of Inherited Thrombocytopenia worldwide." (PMID 34059198, 2021). "Patients with MYH9-RD exhibit varying degrees of thrombocytopenia from birth; exceptional cases display normal numbers, but all clearly exhibit giant platelets." (PMID 33926054, 2021). "Further, elective surgeries in MYH9-RD patients with severe thrombocytopenia have been performed safely after administration of Eltrombopag." (PMID 34059198, 2021). "MYH9-RPD represent a group of hereditary macrothrombocytopenias characterized by thrombocytopenia, giant platelets, and a combination of leukocyte inclusion bodies, hearing loss, nephritis or cataract." (PMID 32950057, 2020). "In Italy, where a large active patient registry was established in 2006, MYH9‐RD has an estimated frequency of 1 in 312,000, representing 12% of the inherited thrombocytopenias." (PMID 31562665, 2020). "Observation of peripheral blood smear for the presence of thrombocytopenia, giant platelets, and granulocyte inclusion bodies (Döhle-like bodies) is highly important for the early diagnosis of MYH9 disorders." (PMID 31885961, 2019). "MYH9-related disease has a variable clinical evolution involving thrombocytopenia and possibly sensorineural deafness, cataract, and/or nephropathy often leading to end-stage renal disease." (PMID 31622367, 2019). "RUNX1, ANKRD26, MYH9, ACTN1, and GP1BB had ranks of 1, 3, 8, 16, and 74, respectively, with none of the other loci in the top 20 ranks being known to be implicated in thrombocytopenia." (PMID 28669401, 2017). "Defects in the MYH9 gene are responsible of different autosomal dominant disorders characterized by thrombocytopenia and platelet macrocytosis." (PMID 26910538, 2016). "Secondly, since in vitro platelet function in MYH9-RD is normal or only slightly reduced, the indication for prophylactic transfusions can be reasonably based on the general recommendations for thrombocytopenias." (PMID 24980457, 2014). "In the control group of patients with MYH9-unrelated inherited thrombocytopenias, 3 out of 32 evaluable patients (9.4%) had an increase of at least one aminotransferase." (PMID 22558294, 2012). "Previous reports have described this variant in association with heterogeneous phenotypes, including primary immunodeficiency and steroid-resistant nephrotic syndrome, but without definitive evidence establishing causality for MYH9-related thrombocytopenia." (PMID 41300679, 2025).